IL22RA1 (interleukin 22 receptor subunit alpha 1)
Description:
Component of the receptor for IL20, IL22 and IL24. Component of IL22 receptor formed by IL22RA1 and IL10RB enabling IL22 signaling via JAK/STAT pathways. IL22 also induces activation of MAPK1/MAPK3 and Akt kinases pathways. Component of one of the receptor for IL20 and IL24 formed by IL22RA1 and IL20RB also signaling through STATs activation. Mediates IL24 antiangiogenic activity as well as IL24 inhibitory effect on endothelial cell tube formation and differentiation.
Synonyms: CRF2-9; IL22R; IL22R1
Tractability: Small molecule: a structure with a bound ligand is known. Antibody: UniProt places it where antibodies can reach, with high confidence; its Gene Ontology location is reachable by antibodies, with high confidence; UniProt predicts a signal peptide or a membrane-spanning region. PROTAC: UniProt records ubiquitination sites on it. Other modalities: a drug acting on it is in phase 2 or 3 trials.
Gene: Protein-coding gene on chromosome 1 (24,119,771 to 24,143,165, reverse strand). Ensembl gene ENSG00000142677.
Subcellular location: Cell membrane
Pathways (Reactome):
Immune System: Interleukin-20 family signaling
Gene Ontology:
Molecular function: protein binding; cytokine receptor activity; interferon receptor activity; interleukin-22 receptor activity; interleukin-20 binding
Biological process: acute-phase response; apoptotic process; cellular response to interleukin-4; cytokine-mediated signaling pathway; negative regulation of inflammatory response; regulation of cell population proliferation; interleukin-22-mediated signaling pathway
Cellular component: interleukin-20 receptor complex; receptor complex; plasma membrane
Genetic constraint (gnomAD): Loss-of-function variants: 25 observed, 32.58 expected, observed/expected ratio (o/e) 0.77, 90% interval 0.56 to 1.07. The upper end of that interval is the gene's LOEUF score, 1.07, which puts it in group 4 of 6, group 1 being the genes least tolerant of losing a copy. Missense variants: 709 observed, 749.95 expected, observed/expected ratio (o/e) 0.95, 90% interval 0.89 to 1.01. Synonymous variants: 305 observed, 311.07 expected, observed/expected ratio (o/e) 0.98, 90% interval 0.89 to 1.08.
Homologues: Orthologues: chimpanzee IL22RA1 (99% identical), macaque IL22RA1 (95% identical), dog IL22RA1 (79% identical), pig IL22RA1 (78% identical), rabbit IL22RA1 (74% identical), mouse Il22ra1 (73% identical), rat Il22ra1 (72% identical), guinea pig IL22RA1 (63% identical), tropical clawed frog il22ra1 (23% identical), zebrafish il22ra2 (10% identical), zebrafish ifnlr1 (10% identical), zebrafish crfb15 (8% identical), and 4 more. Paralogues in human: IL10RA (19% identical), IL20RA (16% identical), IFNLR1 (11% identical), IL22RA2 (11% identical), IFNAR2 (10% identical), IFNGR1 (9% identical), IFNAR1 (9% identical), IL10RB (8% identical), F3 (8% identical), IFNGR2 (8% identical), IL20RB (7% identical).
Diseases named in the same sentence as IL22RA1 in open-access papers:
IL22RA1 is named in the same sentence as 121 diseases in open-access papers, as found by Europe PMC text mining. Sharing a sentence is not in itself a finding about the gene and the disease. The quoted sentences say what the papers report.
pancreatic cancer (10 papers, 2015 to 2024). "IL22RA1 has been reported to promote the stemness and tumorigenicity of pancreatic cancer cells by activating STAT3." (PMID 38098005, 2023). "For example, the expression of IL20RA and IL22RA1 promotes stemness in breast cancer and pancreatic cancer, respectively." (PMID 38098005, 2023). "In pancreatic cancer, IL-22 promoted pancreatic cancer stemness via IL22RA1/STAT3 signalling, establishing the mechanism of regulation of cancer stemness in the tumour microenvironment." (PMID 34572431, 2021). "Interleukin 22 receptor subunit alpha 1 (IL22RA1) and protease serine 3 (PRSS3) were associated with chronic pancreatitis in mouse models and with progression, metastasis, and prognosis of human pancreatic cancer." (PMID 31565069, 2019). "Except for IL22RA1 and PAK3, most of them were up-regulated in pancreatic cancer." (PMID 33869254, 2021). "Pathway analysis of its target genes via DAVID showed enrichment (FDR < 5 %) of genes in the Jak-Stat signaling pathway, including several receptors of interleukins (PTPN6, IL22RA1, CREBBP, IL28RA, IL15RA, PIK3R5, STAT3) and pancreatic cancer pathways (VEGFC, ACVR1B, PIK3R5, EGF, STAT3)." (PMID 26572553, 2015).
colitis (8 papers, 2021 to 2025). Inflammation of the colon. "Together, these results show that exogenous hemopexin has a protective effect in acute colitis and further indicate that hemopexin induction during colitis is dependent on IL-22ra1 signaling." (PMID 40791589, 2025). "Wild-type (Wt) and Il22ra1-/- mice were used to evaluate the effects of exogenous hemopexin and hemin treatments on colitis severity." (PMID 40791589, 2025). "Collectively, our results indicate that IL-22Ra1 signaling in IECs protects mice from DSS-induced development of colitis." (PMID 38733584, 2024). "Further studies are needed to validate our findings in another model of experimental colitis and to explore the importance of IL-22Ra1 signaling in various types of IECs." (PMID 38733584, 2024). "Since other cytokines such as IL-20 and IL-24 also signal through IL-22Ra1, we used Il22−/− mice and observed that these mice were more susceptible to DSS-induced colitis as compared to wild-type controls." (PMID 38733584, 2024). "IL-22 signaling was crucial for the induction of hemopexin in the colon, as Il22ra1-/- mice exhibited limited hemopexin induction and more severe colitis, which could be reversed by recombinant hemopexin administration." (PMID 40791589, 2025). "Despite similar body weights between PBS-treated (control) and hemopexin-treated Il22ra1-/- mice during the experiment, colitis severity was significantly attenuated by exogenous hemopexin treatment as indicated by lower DAI scores and improved colonic lengths when compared to PBS treatment." (PMID 40791589, 2025). "Collectively, our data show that IL-22Ra1 signaling in MATH1+ cells may be important in protecting from DSS colitis by promoting the extension of the O-glycan structure and sialylation." (PMID 38733584, 2024). "Mice lacking IL-17RA and IL-22RA1 exhibited high fungal loads in esophagus- and intestinal tract, severe weight loss, and symptoms of colitis." (PMID 38949991, 2024). "Reversal of colitis symptoms by antagonistic IL-22BP-Fc suggested that signaling through supraphysiological amounts of IL-22 and its receptor IL-22RA1 in the gut is detrimental, and could possibly induce colonic epithelial ER stress and consequent apoptosis." (PMID 34992594, 2021). "We also found that during colitis induction by DSS, IL-22RA1 expression in colonic epithelial cells was greatly enhanced in MSC-/- mice compared with MSC+/+ mice, as detected by immunohistochemistry staining." (PMID 34992594, 2021). "This was evidenced by the limited hemopexin induction in the liver and its reduced presence in the serum and feces of Il-22ra1-/- mice and by the consequent severity of DSS-induced colitis, which could be reversed by recombinant hemopexin treatment." (PMID 40791589, 2025). "By using a range of IEC type-specific Il22Ra1 conditional knockout mice and a dextran sulfate sodium (DSS) colitis model, we demonstrate that IL-22Ra1 signaling in MATH1+ cells (goblet and progenitor cells) is essential for maintaining the mucosal barrier and intestinal tissue regeneration." (PMID 38733584, 2024). "This indicates that IL-22Ra1 signaling in MATH1+ cells (goblet cells) plays an important role in regulating glycosyltransferase-mediated changes in the O-glycan structure of mucin and protecting from the development of colitis." (PMID 38733584, 2024). "Since we observed reduced expression of the B3galt5 gene that promotes mucin type-O glycosylation, we wanted to explore if IL-22Ra1 signaling in MATH1+ cells (predominantly goblet cells in the colon) induces B3galt5 expression and protects mice from DSS-induced colitis." (PMID 38733584, 2024). "Collectively, our data show that the lack of IL-22Ra1 signaling in the Paneth cell is not involved in exacerbating DSS-induced colitis." (PMID 38733584, 2024). "In marked contrast, hemin treatment in Il22ra1-/- mice failed to attenuate colitis severity." (PMID 40791589, 2025).
colitis (continued). "IL-22ra1 expression was detected mainly in goblet cells and enterocytes for both treated and disease controls at similar levels, but interestingly it was noted that I3C treatment increased expression of this receptor component in fibroblasts, which was not present in colitis controls." (PMID 39229279, 2024).
psoriasis (8 papers, 2014 to 2025). An autoimmune condition characterized by red, well-delineated plaques with silvery scales that are usually on the extensor surfaces and scalp. "To date, IL22RA1 had been only associated to inflammatory responses in airway epithelia by genetic studies, and IL20RA to psoriasis." (PMID 31693680, 2019). "However, in psoriasis, only the IL22RA1 subunit is up regulated." (PMID 25208211, 2014). "Moreover, the fact that miR-197 targets only the IL22RA1 subunit of the IL-22 receptor emphasizes the role it might play in the pathogenesis of psoriasis." (PMID 25208211, 2014).
viral infection (8 papers, 2012 to 2025). "Expression of Ras-like estrogen regulated growth inhibitor (RERG) increased while expression of Interleukin 22 receptor subunit alpha 1 (IL22 RA1) genes decreased in bats with WNS, irrespective of viral infection." (PMID 30341341, 2018).
COVID-19 (5 papers, 2022 to 2025). A disease caused by infection with severe acute respiratory syndrome coronavirus 2. "IL22RA1 is a crucial marker, with elevated concentrations associated with increased risk of death in cases of COVID-19." (PMID 40362649, 2025). "IL22RA1 has been identified as a crucial gene for critical COVID-19 and as a significant pathway involving viral protein interactions with cytokines, cytokine receptors such as IL22RA1 and TNFRSF10B, and cytokine–cytokine receptor interactions." (PMID 40362649, 2025).
lung adenocarcinoma (5 papers, 2021 to 2022). A carcinoma that arises from the lung and is characterized by the presence of malignant glandular epithelial cells. "IL22RA1 was negatively associated with monocytes but positively correlated with macrophages M1 in lung adenocarcinoma." (PMID 35874683, 2022). "The expression of the 6 key genes (FKBP3, GPI, LOXL2, IL22RA1, GPR37, has-miR-148a-3p) in lung adenocarcinoma patients with different tumor stages, T stages, N stages and M stages." (PMID 34040139, 2021).
Obesity (4 papers, 2024 to 2025). Accumulation of substantial excess body fat. "Future studies would benefit from studying how IL-22RA1 signaling to additional metabolic organs, such as the pancreas, mediates obesity-associated disorders." (PMID 38383607, 2024). "Here, the authors show in tissue-specific IL-22 receptor knockout mice a key role of intestinal epithelium-specific IL-22RA1 signaling in regulating intestinal metabolism and alleviating obesity-associated disorders." (PMID 38383607, 2024). "In addition, the upregulated hepatic expression of IL-22 receptor (Il22ra1) in Ctrp10 KO female mice may confer protection against obesity-associated fatty liver, inflammation and fibrosis." (PMID 37961647, 2025). "Overall, we elucidate an important regulatory role of intestinal IL-22RA1 signaling in mediating systemic glucose and lipid metabolism after diet-induced obesity." (PMID 38383607, 2024). "To assess the effects of intestinal IL-22RA1 signaling in mediating the onset of diet-induced obesity metabolic disorders, we placed Il22ra1fl/fl;Villin-cre mice on a long-term (16 weeks) HFD." (PMID 38383607, 2024).
cardiac hypertrophy (3 papers, 2017 to 2024). "Third, in mice with myocardial hypertrophy, IL22RA1 levels increase in parallel with markers of myocardial hypertrophy." (PMID 38827362, 2024).
colon cancer (3 papers, 2013 to 2021). "Likewise, there was increased expression of interleukin 28 receptor, α (IL22RA1), which is associated with stage II colon cancer." (PMID 32188695, 2020). "In correlation with overexpression of IL-22 in TILs of CC, IL-22RA1 is also overexpressed in colon cancer cells and in IECs of UC, which ensures the transmission of the IL-22 signal." (PMID 23379788, 2013).
hepatocellular carcinoma (3 papers, 2020 to 2024). A malignant tumor that arises from hepatocytes. "MIN6N8 insulinoma-derived beta cells and hepatocellular carcinoma cell lines, HEPG2 were used to assess the activity of the bispecific drugs and confirm retention of IL-22RA1 activation." (PMID 38811532, 2024).
Insulin resistance (3 papers, 2021 to 2024). Increased resistance towards insulin, that is, diminished effectiveness of insulin in reducing blood glucose levels. "The targeted deletion of IL-22ra1 in pancreatic beta-cells also precipitates age-dependent hyperglycemia, alongside heightened cellular stress and inflammation, without inducing insulin resistance at 20 weeks of age." (PMID 38811550, 2024).
nasal polyps (3 papers, 2021 to 2025). "Identify and compare the frequency of polymorphisms in the IL22RA1 gene (IL22 alpha-1 subunit receptor) among chronic rhinosinusitis patients – either with or without nasal polyps." (PMID 31879195, 2021). "In contrast, an inflammatory role of IL-22 was described in CRS, indicating that IL-22/IL-22Ra1 axis promotes thymic stromal lymphopoietin (TSLP) production under a type-2 microenvironment in airway epithelial cells, potentially contributing to the development of nasal polyps." (PMID 35455762, 2022).
anemia (2 papers, 2022 to 2024). A reduction in the number of red blood cells, the amount of hemoglobin, and/or the volume of packed red blood cells. "Serum levels of IL-22 are increased in patients with anemia secondary to chronic kidney disease and myelodysplastic syndromes, and the IL-22 receptor, IL-22RA1, is present on erythroid precursors, with blockade of IL-22 signaling alleviating anemia in mice." (PMID 39474425, 2024). "Importantly, rIL-22 treatment failed to worsen phenylhydrazine-induced anemia in mice with erythroid cell-specific knockout of IL-22RA1, suggesting that IL-22RA1 expression on erythroid precursors is absolutely involved in the induction of erythroid precursor apoptosis." (PMID 35432360, 2022).
Arthritis (2 papers, 2014 to 2021). Inflammation of a joint. "Il22ra1 mRNA and IL-22R1 protein expression is detected in CD4+ splenocytes from mice with arthritis but not at baseline or during the initiation phase." (PMID 33692792, 2021).
bladder cancer (2 papers, 2021 to 2024). "Furthermore, inflammatory factors IL-20, IL-22RA1, and Eotaxin were significantly associated with an increased risk of bladder cancer." (PMID 39450166, 2024). "Additionally, we found that the inflammatory factor IL-20 and one of its receptors, IL-22RA1, both associated with monocytes, are risk factors for bladder cancer." (PMID 39450166, 2024). "In addition, our findings highlight the role of IL-20 and IL-22RA1, a component of its receptor, in bladder cancer development." (PMID 39450166, 2024).
chronic obstructive pulmonary disease (2 papers, 2024). A chronic and progressive lung disorder characterized by the loss of elasticity of the bronchial tree and the air sacs, destruction of the air sacs wall, thickening of the bronchial wall, and mucous accumulation in the bronchial tree. "Furthermore, both mouse and human studies of chronic obstructive pulmonary disease (COPD) show that IL-22Ra1 expression by macrophages as well as increased IL-22 expression both are associated with exacerbated chronic obstructive pulmonary disease." (PMID 38101567, 2024).
glaucoma (2 papers, 2019 to 2021). Increased pressure in the eyeball due to obstruction of the outflow of aqueous humor. "In the present study, we found that the expression of IL22RA1 was significantly upregulated in glaucoma tissues compared with normal tissues." (PMID 31391457, 2019). "Among those genes, IL22RA1 was predicated to be a target of both miR-760 and miR-215-3p, and its expression was upregulated in the glaucoma tissues when compared with the control tissues." (PMID 31391457, 2019). "Furthermore, through microarray we found IL22RA1 was increased in glaucoma and both of miR-760 and miR-215-3p bound to the 3′ UTR of IL22RA1." (PMID 31391457, 2019). "In conclusion, NR_003923 and IL22RA1 might contribute to glaucoma progression and be a novel and potential biomarkers and therapeutic targets for glaucoma." (PMID 31391457, 2019). "Therefore, NR_003923 and IL22RA1 might contribute to glaucoma progression." (PMID 34244823, 2021).
glioblastoma (2 papers, 2019 to 2022). The most malignant astrocytic tumor (WHO grade IV). "The expression of IL22 was low in glioblastoma and normal tissues, whereas IL22RA1 was increased in primary and recurrent glioblastomas compared with normal tissues." (PMID 35874683, 2022).
influenza (2 papers, 2019 to 2025). An acute viral infection of the respiratory tract, occurring in isolated cases, in epidemics, or in pandemics; it is caused by serologically different strains of viruses (influenzaviruses) designated A, B, and C, has a 3-day incubation period, and usually lasts for 3 to 10 days. "To understand if IL-22Ra1 was a primary or secondary TLR3 response gene we targeted type I interferons as they are the most common TLR3 induced genes after influenza infection." (PMID 31416461, 2019). "Overall, this study provides an important insight into the mechanisms involved in IL-22Ra1 induction and its physiological relevance following influenza infection." (PMID 31416461, 2019). "During influenza infection, the IL-22Ra1 is produced by type II cells in areas of parenchymal injury and inflammation." (PMID 31416461, 2019). "Here we show both in vivo and in vitro that IL-22Ra1 was induced as early as 24 h after influenza (H1N1 PR8) infection." (PMID 31416461, 2019). "Here we demonstrate both in vivo and in vitro that IL-22Ra1 is induced rapidly after influenza infection in a TLR3 dependent manner." (PMID 31416461, 2019). "Here we demonstrate in both mouse and human models that influenza significantly induces IL-22Ra1 but not IL-10Rb (data not shown)." (PMID 31416461, 2019).
insulinoma (2 papers, 2024). "To explore the pathways downstream of IL-22ra1 signaling, we treated MIN6N8 mouse insulinoma beta-cells with IL-22 and performed RNA sequencing." (PMID 38811550, 2024).
lung carcinoma (2 papers, 2019 to 2021). "Our correlation analysis revealed that the correlation between IL22RA1 with macrophage was significantly obvious suggesting that the IL22RA1 might be an immune-related gene in lung carcinoma." (PMID 34040139, 2021).
periodontitis (2 papers, 2024 to 2025). An acute or chronic inflammatory process that affects the tissues that surround and support the teeth. "The results provided genetic evidence for significant associations between genetically predicted levels of family Pasteurellaceae, 45 blood metabolites, and 4 inflammatory proteins (IL-4, IL-22RA1, S100-A12, TNFSF12) and periodontitis susceptibility." (PMID 41001956, 2025).
pulmonary fibrosis (2 papers, 2021 to 2022). Chronic progressive interstitial lung disorder characterized by the replacement of the lung tissue by connective tissue, leading to progressive dyspnea, respiratory failure, or right heart failure. "We measured the IL-22RA1 mRNA level of lung tissues in normal mice and in bleomycin-induced pulmonary fibrosis mice." (PMID 36564791, 2022).
allergic contact dermatitis (1 paper, 2019). An inflammatory skin condition caused by an immune response to direct contact between the skin and an allergen. "To assess their role in ACD, we set up a mouse model of PPD-induced allergic contact dermatitis and we showed that, in contrast to Il22-deficient mice, Il22ra1-, Il20rb- and Il24-deficient mice are partially protected against development of PPD-induced contact hypersensitivity." (PMID 30755657, 2019).